FJX1 (four-jointed box kinase 1)
Diseases named in the same sentence as FJX1 in open-access papers (continued):
Sharing a sentence is not in itself a finding about the gene and the disease.
cystic kidneys (1 paper, 2019). "Taken together, these data suggest that Fjx1 disruption protects the cystic kidneys against kidney failure by reducing inflammation and fibrosis." (PMID 31038742, 2019). "Although we observed significant deregulation of PCP in pre‐cystic kidneys after injury in both single Pkd1 mutant mice and double KO, the additional deletion of Fjx1 did not further change the PCP phenotype in the Pkd1 KO." (PMID 31038742, 2019).
gastric cancer (1 paper, 2023). A primary or metastatic malignant neoplasm involving the stomach. "The mRNA levels of RAI14, GUCY1A2, CNGB3, FJX1, FZD2, ELOVL2, and GDPD4 were all expressed upregulated in gastric cancer tissues, except for CXCL13, whose expression level was not significantly different between gastric cancer tissues and normal cell lines." (PMID 36823639, 2023).
hearing loss (1 paper, 2022). "Other genes were related to BPD-associated outcomes such as retinopathy of prematurity (ROP, e.g., GBP3, FJX1, HIPK2) and hearing loss (e.g., GJB6, TMEM63B) and mitochondrial energy metabolism (e.g., TOMM7, SLC25A26, SLC25A33, PDK1, PKM, MDH1)." (PMID 35484630, 2022).
kidney failure (1 paper, 2019). An acute or chronic condition that is characterized by the inability of the kidneys to adequately filter the blood. "Indeed, Axin2, Cd44, Ccnd1 and to certain extent Myc, showed significantly lower expression in double KO compared with Pkd1 KO mice, both at 10 weeks after DCVC and at kidney failure, suggesting a reduced activation of the canonical Wnt signalling in the absence of Fjx1." (PMID 31038742, 2019).
metastatic cancers (1 paper, 2022). A carcinoma which has spread from the original site of growth to another anatomic site. "Th2 cells were inversely proportional to FJX1 expression in metastatic cancer, according to TCGA data." (PMID 35928453, 2022). "Differences in the immune-infiltrating microenvironment of primary and metastatic cancers based on data from TCGA-COAD revealed a positive correlation between FJX1 and the level of infiltration of most immune cells." (PMID 35928453, 2022). "To summarize, these findings suggest that FJX1 stimulates the formation of tumor fibroblasts and is critical in the progression of metastatic cancer." (PMID 35928453, 2022). "Furthermore, early cancer carcinoma ecotypes include CE6 and CE10, whereas metastatic cancer ecotypes have CE1, CE2, and CE9, indicating that the tumor immune milieu becomes more complicated as FJX1 expression increases." (PMID 35928453, 2022).
non-small cell lung carcinoma (1 paper, 2019). A group of at least three distinct histological types of lung cancer, including non-small cell squamous cell carcinoma, adenocarcinoma, and large cell carcinoma. "This phenotype has been shown in vivo in a non-small cell lung cancer model where Fjx1 overexpression was found to be associated with increased metastasis." (PMID 31236144, 2019).
ovarian carcinoma (1 paper, 2019). A malignant neoplasm originating from the surface ovarian epithelium. "Indeed, besides our own microarray dataset (GSE13597), we found that FJX1 is also overexpressed in independent NPC microarray dataset (GSE12452) (2.8 fold), as well as colorectal and ovarian cancers (2.4- and 2.3-fold, respectively; p < 0.01) when compared to normal tissues." (PMID 31236144, 2019).
rectal cancer (1 paper, 2013). A primary or metastatic malignant neoplasm that affects the rectum. "In the present study, we identified four jointed box 1, FJX1, as a gene whose expression was inhibited in human rectal cancers in response to celecoxib treatment." (PMID 23922772, 2013).
stomach adenocarcinoma (1 paper, 2023). "The FJX1 gene alterations data were obtained from the cBioPortal, which suggested that the highest alteration frequency of FJX1 was more than 4% and the “amplification” was the primary genetic alteration type in stomach adenocarcinoma." (PMID 37324001, 2023).
cancer (8 papers, 2013 to 2023). A tumor composed of atypical neoplastic, often pleomorphic cells that invade other tissues. "Our study indicated that FJX1 expression was high in most cancers and was significantly associated with poor prognosis." (PMID 37324001, 2023). "All the investigations indicated that FJX1 expression was significantly upregulated in most cancers and associated with tumor stage." (PMID 37324001, 2023). "The Four Jointed Box 1 (FJX1) gene has been implicated in the upregulation of various cancers, highlighting its crucial role in oncology and immunity." (PMID 37324001, 2023). "Specifically, high expression of FJX1 is associated with a more immunotherapy-tolerant microenvironment and lower overall survival in cancer patients." (PMID 37324001, 2023). "An orthologue of human FJX1, the four-jointed (fj) gene in Drosophila and Fjx1 in mouse, has reported to be associated with cancer progression pathways." (PMID 31236144, 2019). "We also discovered that FJX1 is closely linked with cancer and immunity pathways." (PMID 37324001, 2023). "Although the exact function of FJX1 in human is not fully understood, data from the developmental studies suggests that the function of FJX1 in cancer development could be linked to its role in promoting growth and cell movement." (PMID 31236144, 2019). "Therefore, our pan-cancer prognosis value analysis of FJX1 demonstrates that it could be an underlying and novel diagnostic and prognostic biomarker for cancers." (PMID 37324001, 2023). "We believe that the pan-cancer analysis of FJX1 can provide new insights into the development of novel therapeutic strategies for cancer treatment." (PMID 37324001, 2023). "Simultaneously, the radar charts displayed that the mean FJX1 expression in cancers was 7.3, while the mean FJX1 expression in normal tissues was 4.97." (PMID 37324001, 2023). "Our study underscores the importance of FJX1 as a potential biomarker for cancer diagnosis and prognosis." (PMID 37324001, 2023). "In this study, we conducted a comprehensive analysis of the relationship between FJX1 expression and various types of cancer using pan-cancer data from The Cancer Genome Atlas (TCGA) and Genotype-Tissue Expression (GTEx) databases." (PMID 37324001, 2023). "In BLCA, BRCA, CHOL, COAD, ESCA, HNSC,SARC, KIRC, KIRP, LIHC, STAD, and THCA, the FJX1 expression in cancer was significantly higher than in paracancerous tissues." (PMID 37324001, 2023). "The FJX1 expression of cancer tissues correlation with normal tissues were explored by TCGA and GTEx." (PMID 37324001, 2023). "We found that FJX1 expression was significantly correlation with vast majority of MHC genes (21 types) in most cancers." (PMID 37324001, 2023). "Our research suggests that FJX1 plays a significant role in the development of drug resistance in 6 and 10 types of cancer, by affecting TMB and MSI, respectively." (PMID 37324001, 2023). "In order to better understand the biological function of FJX1 and identify new immunotherapy targets for cancer, we conducted a comprehensive analysis of this gene." (PMID 37324001, 2023). "According to our results, FJX1 was found to be altered in 19 types of cancer, with amplification being the most common genetic alteration across different cancer types." (PMID 37324001, 2023). "While our article highlights the significance of FJX1 as a biomarker for carcinogenicity and prognosis in various types of cancer, there are some important limitations to our study." (PMID 37324001, 2023). "Our results indicated that FJX1 is a critical prognostic factor in various cancers and plays a crucial role in tumor immunity." (PMID 37324001, 2023). "We discovered that in most cancers, the FJX1 expression positively related with different subtypes of tumor macrophages (TAMs) but negatively related with different subtypes of B and T cells." (PMID 37324001, 2023).
cancer (continued). "Our results highlight the importance of further exploring the potential of targeting FJX1 as a therapeutic strategy in cancer." (PMID 37324001, 2023). "Overall, our findings provide new insights into the role of FJX1 in cancer immunotherapy and drug resistance." (PMID 37324001, 2023). "A study of Liu F. and colleagues showed that inhibition of lncPVT1 expression was able to suppress cancer progression acting on the miR-106b-5p/FJX1 axis." (PMID 35090471, 2022). "Our study has revealed that the expression of FJX1 has a significant correlation of cancer cell proliferation and enhances anchorage-independent growth." (PMID 31236144, 2019). "In this study, we identified FJX1 to be overexpressed in NPC, and exogenous expression of FJX1 conferred a survival advantage to cancer cells." (PMID 31236144, 2019). "Our results demonstrate that these peptides are immunogenic and peptide stimulated T-cells were able to induce peptide-specific cytolytic activity specifically against FJX1-expressing cancer cells." (PMID 26536470, 2015). "While the exact function of human FJX1 is currently unclear, recent reports have suggested a possible functional role in cancer pathogenesis." (PMID 26536470, 2015). "Our results suggest that these peptides are capable of inducing specific cytotoxic cytokines secretion against FJX1-expressing cancer cells and serve as a potential vaccine-based therapy for NPC patients." (PMID 26536470, 2015). "Our findings are consistent with these studies, as our pan-cancer analysis revealed high FJX1 expression in 22 types of cancer, and it was correlated with poor overall survival, disease-specific survival, disease-free interval, progression-free interval, and worse overall survival in some cancers." (PMID 37324001, 2023). "In addition, FJX1 also had significant positive correlation with immune-related pathways and DNA damage repair-related pathways in most cancers." (PMID 37324001, 2023). "High FJX1 expression may contribute to an immunosuppressive microenvironment, and targeting FJX1 could be a promising approach for immunotherapy in cancer treatment." (PMID 37324001, 2023). "Explorations on the function of FJX1 in human cancers have been widely performed." (PMID 36825005, 2023). "Moreover, the survival curve displayed that high FJX1 expression indicated worse overall survival time in 16 types of cancer." (PMID 37324001, 2023). "FJX1 expression was positive relevant with large number of infiltrated immune cells, such as monocyte cells, NKT, macrophages, and Th2, while there was negative association with CD8+ T cells and B cells in various cancers." (PMID 37324001, 2023). "Inversely, FJX1 expression in cancer was lower than in paracancerous tissues only in KICH." (PMID 37324001, 2023). "Therefore, further investigation is necessary to confirm the relationship between FJX1 and the immunosuppressive microenvironment in human cancers." (PMID 37324001, 2023). "This demonstrated that PV1 may be an effective vaccine for the treatment of HNSCC and other cancer patients with FJX1 overexpression." (PMID 36825005, 2023). "FJX1 is an angiogenesis regulator whose expression levels are elevated in a variety of cancers." (PMID 35928453, 2022). "As a dysregulated gene in one cancer is typically also dysregulated in other types of cancer, we sought to explore whether this is also the case for FJX1." (PMID 31236144, 2019). "In this study, we also demonstrated that FJX1 could increase the invasive potential of cancer cells." (PMID 31236144, 2019). "Therefore in this study, we chose to design FJX1-specific HLA-A2-restricted peptides and MHC class II HLA-DR restricted long peptides and these was then evaluated as potential cancer vaccine targets in FJX1 overexpressing NPCs." (PMID 26536470, 2015). "Our data also suggests that these peptides could be a potential treatment strategy for NPC patients and might also benefit other cancers overexpressing FJX1." (PMID 26536470, 2015).
cancer (continued). "In this study, we designed 6 MHC class I (HLA-A2 restricted) and 2 MHC class II (HLA-DR restricted) FJX1-derived sequence specific peptides (9–20 amino acids) and evaluated in vitro, their potential to stimulate NPC patient’s immune response towards target cancer cell lines overexpressing FJX1." (PMID 26536470, 2015). "Despite these observations of increased FJX1 mRNA expression in other carcinomas, the cellular source, biological function of FJX1 and its effects on tumor progression are unknown." (PMID 23922772, 2013). "Additionally, we analyzed the FJX1 expression in cancer and para-cancerous tissues." (PMID 37324001, 2023). "To investigate whether FJX1 affects the immunotherapy effect in cancer patients, we downloaded the immunotherapy dataset from IMvigor210CoreBiologies and found that in the immunotherapy-tolerant group, the FJX1 expression was higher compared with immunotherapy-effective group (p<0.05)." (PMID 37324001, 2023). "Interestingly, a recent study found that FJX1-specific peptides can inhibit the proliferation of high FJX1 expression cancer cells and may serve as a potential immunotherapy for NPC patients." (PMID 37324001, 2023). "Comparing HeLa/T cells overexpressing FJX1 to those transfected with vector alone, we demonstrated that a high expression of FJX1 resulted in a significant increase in the number of colonies formed (p = 0.04), suggesting that FJX1 can contribute to a more aggressive phenotype in cancer." (PMID 31236144, 2019). "Notwithstanding, elevated levels of FJX1 in NPCs and other cancers, and combined with the minimal expression in normal human vital organs suggested that this tumor antigen may have value for developing a cancer vaccine that offered benefit as well as fewer side effects to NPC patients." (PMID 26536470, 2015). "The promoter methylation levels of FJX1, KLHL35, and IER5L in primary malignant tumors were higher than those in normal tissues." (PMID 35928453, 2022). "From this study, several potential oncogenes or candidate biomarkers such as FJX1, WNT5A, CLDN1, FGFR3, FZD6, RALA, and CLCA2 were shortlisted based on previous reports on their involvement in cancer pathophysiology, neoplasia, and embryogenesis process." (PMID 31236144, 2019). "In this study, we show that FJX1 is overexpressed at both the mRNA and protein levels in a subset of primary NPC tumours, as well as in other cancers." (PMID 31236144, 2019). "FJX1 is considered a candidate for the regulation of angiogenesis and tumorigenesis-related pathways such as Notch, JAK/STAT, and Hippo-YAP in several human cancers." (PMID 36825005, 2023). "Additionally, FJX1 mRNA expression was positively correlated with CNA and negatively correlated with DNA methylation in 18 and 22 types of cancer, respectively." (PMID 37324001, 2023). "The evaluation of FJX1 as an immunotherapy target for NPC and other cancers is currently ongoing." (PMID 31236144, 2019). "The normal epithelium in the control samples and the normal epithelium adjacent to carcinoma were consistently negative for the expression of FJX1 in all 11 nonmalignant samples." (PMID 31236144, 2019). "Although with a limited sample number, our results demonstrate that the FJX1-derived peptides are immunogenic and able to induce anti-tumor immune responses in NPC patients against FJX1-expressing tumor cells irrespective of cancer type." (PMID 26536470, 2015). "Furthermore, our results indicate that FJX1 is positively correlated with the expression of MHC genes, immunosuppressive genes, chemokines, chemokine receptors, and immunosuppressive pathway-related genes in most TCGA cancers." (PMID 37324001, 2023). "Broadly, FJX-1 specific might be beneficial for cancers expressing FJX-1 regardless of the cancer origin." (PMID 26536470, 2015). "However, the potential for FJX1 as a target for developing cancer vaccines as an alternative therapy for NPC has not been explored." (PMID 26536470, 2015).
cancer (continued). "Additionally, FJX1 expression was significantly and positively correlated with immunosuppressive genes (TGFB1 and IL-10), chemokines (CCR1 and CCR5), chemokines receptors (CCL2 and CXCL5), and immunosuppressive pathway-related genes (TFGB1 and WNT1), in most TCGA cancers." (PMID 37324001, 2023). "FJX1 expression was positive relation with stromal score, ESTIMATE sore, and immune score in 17, 14, and 10 kinds of cancer, respectively (p<0.05), while there was a negative correlation with tumor purity in 13 kinds of cancer (p<0.05)." (PMID 37324001, 2023).